SHISA5 (shisa family member 5)
Synonyms: SCOTIN; hShisa5
Tractability: Antibody: UniProt predicts a signal peptide or a membrane-spanning region. PROTAC: ubiquitination databases record sites on it.
Gene: Protein-coding gene on chromosome 3 (48,467,798 to 48,504,826, reverse strand). Ensembl gene ENSG00000164054.
Subcellular location: Endoplasmic reticulum membrane; Nucleus membrane
Pathways (Reactome):
Metabolism of proteins: Post-translational protein phosphorylation; Regulation of Insulin-like Growth Factor (IGF) transport and uptake by Insulin-like Growth Factor Binding Proteins (IGFBPs)
Gene Ontology:
Molecular function: molecular condensate scaffold activity; protein binding
Biological process: positive regulation of canonical NF-kappaB signal transduction; positive regulation of endoplasmic reticulum unfolded protein response; positive regulation of response to endoplasmic reticulum stress; regulation of COPII vesicle uncoating; regulation of ER to Golgi vesicle-mediated transport
Cellular component: endoplasmic reticulum; endoplasmic reticulum lumen; endoplasmic reticulum membrane; nuclear envelope; nuclear membrane
Genetic constraint (gnomAD): Loss-of-function variants: 21 observed, 26.52 expected, observed/expected ratio (o/e) 0.79, 90% interval 0.56 to 1.14. The upper end of that interval is the gene's LOEUF score, 1.14, which puts it in group 5 of 6, group 1 being the genes least tolerant of losing a copy. Missense variants: 302 observed, 311.15 expected, observed/expected ratio (o/e) 0.97, 90% interval 0.88 to 1.07. Synonymous variants: 125 observed, 126.72 expected, observed/expected ratio (o/e) 0.99, 90% interval 0.85 to 1.14.
Homologues: Orthologues: chimpanzee SHISA5 (99% identical), macaque SHISA5 (93% identical), pig SHISA5 (82% identical), dog SHISA5 (80% identical), rabbit SHISA5 (79% identical), guinea pig SHISA5 (77% identical), rat Shisa5 (66% identical), mouse Shisa5 (65% identical), tropical clawed frog uhrf2 (25% identical). Paralogues in human: UHRF1 (27% identical), UHRF2 (27% identical).
Diseases named in the same sentence as SHISA5 in open-access papers:
SHISA5 is named in the same sentence as 12 diseases in open-access papers, as found by Europe PMC text mining. Sharing a sentence is not in itself a finding about the gene and the disease. The quoted sentences say what the papers report.
Sepsis (2 papers, 2023). Sepsis is defined as life-threatening organ dysfunction caused by a dysregulated host response to infection. "In the sepsis group, the genes related to significant AS events, such as, SHISA5 and IFI27, were mostly enriched in the cell apoptosis pathway." (PMID 37749550, 2023). "We observed that IFI27 and SHISA5, both apoptosis-related genes, were controlled by the 5pMXE AS pattern and showed significant differential expression levels in sepsis when compared to the healthy group and the infection group." (PMID 37749550, 2023).
migraine (1 paper, 2023). "For kidney function, 19 significant tissue–gene pairs were found for migraine and eGFR using GTEx tissues, including four genes (TREX1, SHISA5, PRR13, TMA7) mainly expressed in tissues of the nervous and cardiovascular system." (PMID 37306871, 2023).
infection (3 papers, 2016 to 2024). The state of being infected such as from the introduction of a foreign agent such as serum, vaccine, antigenic substance or organism. "The upregulation of genes upstream of the cellular apoptosis such as FAS and SHISA5 enhanced the programmed death of the infected cell resulting in reducing inflammation, infection elimination, and prompt tissue repair." (PMID 38394169, 2024).
tumor (3 papers, 2022 to 2025). "The expressions of SHISA5, SERPINE1, and IL1A were markedly high in tumor tissues, whereas those of TP53AIP1, ETS2, and FOS were high in the normal tissues." (PMID 38435998, 2024).
cancer (2 papers, 2021 to 2024). A tumor composed of atypical neoplastic, often pleomorphic cells that invade other tissues. "The role of SHISA5 and SLN in cancers has not been previously studied." (PMID 33611848, 2021).
SHISA5 also shares sentences with these, for which no sentence is quoted: glioma (3 papers); diabetes (1); hepatocellular carcinoma (1); ischaemic cardiomyopathy (1); Obesity (1); thyroid cancer (1); thyroiditis (1).